CD4 (CD4 molecule)
Diseases named in the same sentence as CD4 in open-access papers (continued):
Sharing a sentence is not in itself a finding about the gene and the disease.
Opportunistic infection (continued). "A rapid and accurate CD4+ T lymphocyte count may be required to rapidly begin treatment, determine the status of the infection, and prevent potential opportunistic infections during a single hospital visit." (PMID 39768973, 2024). "After the HIV invades the human body, it targets CD4+ T cells and disrupts the immune system by replicating extensively and changing the permeability of cell membranes, thereby increasing the likelihood of various opportunistic infections." (PMID 38350942, 2024). "CD4+ T-cell depletion is a hallmark of HIV infection, leading to impairment of cellular immunity and opportunistic infections, but its contribution to SIV/HIV-associated gut dysfunction is unknown." (PMID 36813761, 2023). "The prevalence of musculoskeletal disorder was moderate and the following factors are clinically significantly associated with musculoskeletal disorders among ART patient who are following at ART clinic: Recent CD4 count, opportunistic infection, ART regime at initiation and ART regime change." (PMID 37596525, 2023). "Historically, the commencement of ART was delayed until CD4 counts dropped below 200, a level at which opportunistic infections may thrive." (PMID 37884997, 2023). "Participants living with HIV often received their infectious disease care at other institutions, and data on CD4 counts, viral loads, prior opportunistic infections, and current therapies were frequently missing, which prevented analysis for interactions between HIV control and breast cancer care." (PMID 38051529, 2023). "By employing spirometric measurements, we seek to identify patterns of lung impairment, investigate potential associations with disease severity, and explore the impact of various factors, including CD4 count and opportunistic infections, on the respiratory health of these children." (PMID 38022158, 2023). "This is common with the finding of other studies, this may be due to the fact that female patients receive HAART at an early stage, reducing the incidence of opportunistic infections as well as achieving rapid CD4 cell recovery." (PMID 37716975, 2023). "The results showed that CD4+ T cell count ≤ 200/μL, smoking, intravenous drug use, unemployment, male sex, senior citizen status, advanced WHO stage, low level of education, and presence of other opportunistic infections increased the risk of TB among PLHIV." (PMID 37674103, 2023). "In addition, lower access to HIV clinical services reported by all these articles would result in higher HIV transmission, higher opportunistic infections, lower CD4 cell counts, and lower viral suppression." (PMID 36609313, 2023). "Risk factors for HIV/TB co-infection included CD4+ T cell count ≤ 200/μL, smoking, intravenous drug use, unemployment, male sex, senior citizen status, advanced WHO stage, low level of education, and presence of other opportunistic infections." (PMID 37674103, 2023). "On the opposite side of the spectrum, low CD4+ T-cell counts are not systematically associated with opportunistic infections." (PMID 36813761, 2023). "There was CD4 significance at D28 (specific for opportunistic infections) for 128 participants, which may explain post-covid symptoms." (PMID 37928473, 2023). "The category with the positive sign of estimate had a higher CD4 cell count than its counterpart for categorical variables like opportunistic infection patients and TB co-infected patients, and the category with the negative sign of assessment had a lower CD4 cell count than its counterpart." (PMID 38087261, 2023). "Hence, lymphopenia is a well-known factor associated with both viral and bacterial infections, and high blood lymphocyte count (CD4+ T > 500/mm3) at the time of KT and during follow-up has been showed to be protective against opportunistic infections." (PMID 36747162, 2023).
Opportunistic infection (continued). "In addition to ART, late presenters, particularly those with a CD4 count below 200 cells/mm3, are often prescribed additional medicines to treat or prevent opportunistic infections." (PMID 37351535, 2023). "Treating all HIV positive cases regardless of their CD4 status reduces the risk of opportunistic infections including TB." (PMID 37254064, 2023). "In patients with HIV/HTLV-1 co-infection, higher CD4 cell count could lead to misinterpretation of immune status and delay the initiation of prophylaxis against opportunistic infections, with a significant impact on morbidity and mortality." (PMID 37513716, 2023). "In order to minimize HIV replication, HAART employs a mix of antiretroviral medications; as a result, the CD4+ helper T-cell population typically recovers, leading to a decrease in opportunistic infections, an improvement in quality of life, and decreases in morbidity and death." (PMID 37763724, 2023). "Due to the depletion of T-helper lymphocytes (CD4+ cells), reduced activity of CD8+ cytotoxic T cells, and decreased production of type 1 cytokines, HIV-infected patients are at greater risk of developing opportunistic infections." (PMID 36678458, 2023). "In the bi-variable analysis, eleven variables (occupation, WHO clinical stage, nutritional status, CD4 count, opportunistic infection, disclosure status, enrollment type, ART drug adherence, drug side effect, anemia, and isoniazid preventive therapy) were found to be associated at a P-value of 0.2." (PMID 37885727, 2023). "Also, poor adherence to ART fails to prevent further viral destruction of the cellular immune system, with a consequent reduction in the level of CD4 + cells and the development of opportunistic infections." (PMID 36411424, 2022). "Thus, analysis of CD4+ T cells and Tregs should be performed in sarcoidosis patients with overt opportunistic infections." (PMID 34993476, 2022). "Therefore, patients with low CD4 counts are likely to experience opportunistic infection and have a poorer tolerance for therapy." (PMID 36151562, 2022). "Patients with AHD are at high risk of death from opportunistic infections (mostly tuberculosis, severe bacterial infections, and cryptococcal meningitis) even if they are on ART, and this risk increases with the reduction in CD4 cell count." (PMID 36209058, 2022). "Therefore, any conditions that lower CD4 cell counts will weaken the immune systems of children with HIV who are vulnerable to the development of opportunistic infections." (PMID 36536709, 2022). "Additionally, a recent study on Toxoplasma infection revealed that the absence of PD-1 signaling promotes an increase in IL-10 production by CD4+ and CD8+ T cells, which increases the susceptibility to other opportunistic infections." (PMID 35812458, 2022). "One opportunistic infection appeared in a patient with CD4+T lymphocyte count < 150 cells/ul." (PMID 36419079, 2022). "In addition, HIV waned the immune system and accelerated viral replication for the depletion of CD4 count, which precipitated the new episode of lethal opportunistic infections." (PMID 35132323, 2022). "Therefore, the body is vulnerable to opportunistic infections when the CD4 cell count is below 200 or 350 cells/μL." (PMID 36136643, 2022). "CD4+ T-cell counts and the duration of the medications were two important confounders that might significantly affect the prevalence of orofacial opportunistic infections." (PMID 36231240, 2022). "The reason for the observation may be because subjects who have low CD4 count are prone to opportunistic infection which may lead to poor growth." (PMID 36060839, 2022). "In addition, patients a lower preoperative CD4+/CD8+ lymphocyte ratio subsequent develop postoperative infection complications, representing a susceptible population for opportunistic infection." (PMID 36169250, 2022).
Opportunistic infection (continued). "The purpose of the study was to determine the prevalence of HTLV-1 infection in patients attending the HIV Clinic and to compare the CD4+ counts and opportunistic infections of HIV-1/HTVLV-1 coinfected patients versus HIV-1 singly infected patients at the initial visit to the HIV Clinic." (PMID 36363801, 2022). "Lastly, when BL is linked to HIV, patients typically have a CD4 count greater than 200 without concomitant opportunistic infections." (PMID 36620831, 2022). "Although chronic inflammatory conditions and secondary infections can occur in cats with low CD4+ cell counts, the classic opportunistic infections seen in HIV patients (cryptococcosis, Pneumocystis pneumonia and Mycobacterium avium complex infections) are rarely diagnosed in FIV‐infected cats." (PMID 35578381, 2022). "With such low CD4 counts, the ability of the immune system to work against opportunistic infections such as respiratory tract infection is compromised, and this could be attributed to the observed findings in this study." (PMID 36415339, 2022). "The short period of time to achieve undetectability and CD4 lymphocyte count >200/μL (less than two months in both cases) should be noted, leading patients to a clear decrease in the possibility of opportunistic infections in the first six months after starting antiretroviral therapy." (PMID 36078925, 2022). "Consequently, it initiates downstream immune activation and causes local and systemic inflammation, thereby continuously consuming CD4 cells and concurrent symbiosis opportunistic infections of bacteria and other diseases." (PMID 35129067, 2022). "However, in some patients, the CD4 count decreases during chemotherapy, so we should pay attention to the occurrence of opportunistic infections in patients with low baseline CD4 counts." (PMID 36151562, 2022). "Studies show that treatment interruptions might lead to a drop in CD4 counts, increased incidence of opportunistic infections, and mortality, while others argue that guided treatment interruptions might be a successful strategy in long-term HIV care." (PMID 35905123, 2022). "The indicators may be immunological (viral suppression, improved quality of care, maintaining normal CD4 counts, and suppression of opportunistic infections." (PMID 33789618, 2021). "Studies have shown that VL is a better predictor of HIV morbidity and mortality among PLWHA compared to CD4 cell count and a risk factor for opportunistic infections, irrespective of CD4 cell count." (PMID 34176245, 2021). "Also, in a few series, a small proportion of pediatric and adult patients had opportunistic infections and/or a low CD4 T-cell count, and those patients should actually be classified as a combined immunodeficiency." (PMID 33833753, 2021). "This may indicate bias in the data on mortality by CD4 category, for example, potentially due to better management of opportunistic infections, but we were unable to determine specific mechanisms for that apparent bias." (PMID 34546644, 2021). "On the other hand, children who had co-trimoxazole non-user will face several problems such as treatment failure, CD4 count depletion, and the occurrence of opportunistic infection that could lead to death." (PMID 34932563, 2021). "Lymphopenia is a well-known factor associated with both viral and bacterial infections, and in a recent cohort study including 538 KTR, high blood lymphocyte count (CD4+ T > 500/mm3) at the time of transplant and during follow-up were protective factors against opportunistic infections." (PMID 33858369, 2021). "CD4+ T-cell depletion also drives opportunistic infections, cancers, and comorbidities." (PMID 34367156, 2021). "Although low CD4 cell count and inverted CD4/8 ratio were commonly found in these patients, both were not prognostic and their association with the onset of opportunistic infection was not established." (PMID 34113351, 2021).
Opportunistic infection (continued). "Besides, a multicenter observational research finding on CD4 count reduction indicated that one episode of opportunistic infection other than TB demoted CD4 count 54–57 cells/μl and led to substantial increment for active TB incidence." (PMID 34545289, 2021). "The coexistence of TB, Candidiasis, and Cryptococcus neoformans may be explained by the devastating impact of HIV infection on CD4+ cell population's which has an important role in controlling such opportunistic infections." (PMID 32963654, 2020). "Therefore, development of methods to monitor the decline in CD4 count would be extremely important, especially in subjects with co-infections or opportunistic infections." (PMID 33177659, 2020). "On the other hand, viral suppression, coupled with both reduced opportunistic infections and good recovery of CD4 levels, could provide a sensation of absolute well-being and health trust that in return pushes such participants to be less adherent." (PMID 31971957, 2020). "Perceived stigma, widowed marital status, being symptomatic, fair and poor adherence, recent opportunistic infection, low CD4 count and non-disclosed HIV status were associated with depression." (PMID 32742304, 2020). "Since the availability of highly active antiretroviral therapy (HAART), IRIS has been described as the paradoxical worsening of treated opportunistic infections or the unmasking of previously untreated infections, occurring classically when CD4+ T-cell counts rise and function improves." (PMID 33204743, 2020). "Notably, both studies lack data on HIV-related parameters such as antiretroviral therapy (ART) use, HIV-1 viral load, CD4 T cell count, and prior opportunistic infections, all of which are important confounders." (PMID 33083001, 2020). "Thus, patients who started at elevated CD4 count are less likely to develop opportunistic infections, hence less likely to develop clinical and immunologic failures." (PMID 32462003, 2020). "Higher CD4 level is guarantee to prevent opportunistic infection and decrease viral load." (PMID 33175902, 2020). "A retrospective 5-years cohort conducted in India, however, revealed that the presence of opportunistic infection, lower BMI, and low CD4 count at ART initiation were predictors of first-line ART failure with a failure rate of 7.69% and incidence of first-line ART failure 2.09 per 1000 person-years." (PMID 33133585, 2020). "Looking a closer at the distribution of undernutrition with patients’ clinical characteristics, undernutrition was higher in patients with WHO clinical stage three (43%), patients with a CD4 cell count <200 cells/mm3 (67%) and patients with past opportunistic infections (OI’s) (62%)." (PMID 32163485, 2020). "Body mass index, weight for height, ART group, baseline, CD4+ lymphocyte count, occurrence of opportunistic infections (OIs), WHO clinical staging, viral load, nutritional status, and exposure to antitubercular drugs were associated with CD4+ lymphocyte count change on binary linear regression." (PMID 32855823, 2020). "This could be described by the fact that poor ART adherence reduces immunity (CD4) and increases the occurrence of opportunistic infection." (PMID 33489367, 2020). "Besides, patients with low CD4 cell counts are likely to be in WHO stage 3 or 4, a group prone to opportunistic infections and an elevated risk of mortality." (PMID 32255796, 2020). "The age distribution of the included patients did not change significantly throughout the study period, while the proportion of the patients with CD4 lymphocyte counts less than 200 cells/μL and concurrent opportunistic infections decreased with time (p = 0.043 and 0.024, respectively)." (PMID 32530918, 2020). "This could be because of HIV induced depletion of CD4+ T lymphocytes leads to impaired cellular immunity and increased vulnerability to opportunistic infections like TB or reactivation of the latent TB even in the presence of ART." (PMID 32380957, 2020).
Opportunistic infection (continued). "Three patients (2.5%), who presented with advanced immunocompromised state (CD4 count, 0, 21, and 57 cells/μl, respectively) and other serious opportunistic infections (1 pneumocystosis, 1 CMV colitis, and 1 both), died within three months of the HIV diagnosis." (PMID 32530918, 2020). "The CD4 lymphocyte count serves as a laboratory indicator for assessing the immunity of HIV patients, those with less than 350 cells/μl are more susceptible to opportunistic infections." (PMID 32496735, 2020). "Another possible reason could be those patients with low CD4 count may have experienced additional opportunistic infections which might have contributed to fatigue." (PMID 32295546, 2020). "However, the WHO has recently re-affirmed the continued importance of CD4 testing for clinical patient and opportunistic infection management, identification of patients with advanced HIV disease, and in areas with limited access to viral load testing." (PMID 31276477, 2019). "In this instance, CD4 testing informs the prioritising of ART initiation in patients with a CD4 ≤ 350 cells/μL, and determines the need for opportunistic infection prophylaxis (at a CD4 count of ≤200 cells/μL) and for testing for cryptococcal antigenaemia (at a CD4 count of ≤100 cells/μL)." (PMID 30764808, 2019). "Fewer than half of the respondents could link the contribution of cART to the decreasing incidence of opportunistic infections (44.4%), reduction of viral loads (31%) and the increase in CD4 cell counts (29.2%)." (PMID 31534787, 2019). "Studies showed that factors such as unemployment, age, CD4 count, sex, educational status, drug side effects, family/social support, stigma, stage of HIV, living companion, marital status, monthly income and opportunistic infection were predisposed HIV/AIDS patients to depression." (PMID 31429805, 2019). "The possible explanation could be women with lower CD4 count might have decreased immunity which intern leads to the development of opportunistic infections which increases the development of signs & symptoms of disease and visiting of health facility." (PMID 31744548, 2019). "The improvement of depressive symptomatology may thus possibly be attributed to the first year of ARV therapy with subsequent lowering of viral load, improvement of CD4, resolution of opportunistic infections and improvement of life quality." (PMID 31402989, 2019). "Sexual transmission explained 98% of cases, the mean of age between HIV diagnosis and death was 6.2 ± 6.2 years; 72% had CD4 count <200/mL at diagnosis; 43.3% had opportunistic infections (OI) at diagnosis; 64% receipt HAART at any time; 19.4% reached viral load suppressed at any time." (PMID 30941891, 2019). "This could be due to having advanced opportunistic infection/co-infection which may deplete CD4 counts and compromise immunity and may negatively affect response to treatment." (PMID 31687474, 2019). "Intensive chemotherapy may expose patients to opportunistic infections by reducing CD4+ cell counts." (PMID 30926889, 2019). "Reduction in the absolute number of CD4 T cells occurs as one of the earliest immunologic abnormalities of HIV infection, and it is the most important prognostic indicator for risk of developing opportunistic infections." (PMID 31565107, 2019). "The competing risk analysis did not detect any association between EOT levels of NK, CD8 or CD4 and serious and/or opportunistic infections." (PMID 31412798, 2019). "Altogether, these data demonstrate the negative prognostic value of CD4+ lymphopenia and its significance as a predictor of non-response to chemotherapy suggesting the important role of CD4+ T cells in controlling tumor progression and/or development of opportunistic infections in cancer patients." (PMID 30922400, 2019).